TLR4 (toll like receptor 4)
Diseases named in the same sentence as TLR4 in open-access papers (continued):
Sharing a sentence is not in itself a finding about the gene and the disease.
thyroid cancer (5 papers, 2021 to 2025). "TLR4 with the largest coefficient, was found to be significantly upregulated in ATC and was associated with poor prognosis in patients with thyroid cancer." (PMID 37990304, 2023). "Likewise, we found that the up-regulation of TLR4 was positively correlated with ICD score in ATC, and significantly correlated with the poor prognosis of thyroid cancer patients." (PMID 37990304, 2023).
Ventriculomegaly (5 papers, 2018 to 2024). An increase in size of the ventricular system of the brain. "Furthermore, at physiological concentrations, intracerebroventricular delivery of metHgb activates TLR4 homodimers or TLR4/2 heterodimers, promoting nuclear translocation of NF‐κB as well as secretion of TNFα and IL‐1β, and is sufficient to cause ventriculomegaly." (PMID 39450988, 2024). "This Na+/K+-ATPase isoform has previously been implicated in LPS/TLR4/NF-κB-mediated immune responses, a form of which represents a key step in the previous animal model of IVH-induced, NKCC1-mediated ventriculomegaly." (PMID 35948938, 2022).
viral pneumonia (5 papers, 2018 to 2024). Inflammation of the lung parenchyma that is caused by a viral infection. "Alterations in genes involved in the destruction of bacteria (LYST) and bacterial detection by the immune system (TLR6 and TLR4) could possibly increase susceptibility to bacterial infections secondary to viral pneumonia." (PMID 37985737, 2023). "In this study, we found that the inflammatory factors in the lungs of mice with viral pneumonia were disordered, the lungs were damaged, and the TLR4 pathway was significantly activated." (PMID 36504796, 2022). "The results of this study showed that LHQW treatment reduced the viral loads and adjusted inflammatory factors in the lungs, alleviated lung injury, and inhibited the activation of the TLR4/NF-κB signalling pathway in viral pneumonia mice." (PMID 36504796, 2022). "Thus, when B4 bound to TLR4, it will prevent the virus from activating TLR4, which may be an alternative strategy to treat FM1-induced viral pneumonia." (PMID 32625244, 2020). "In the present study, we find that OMT can significantly decrease the expressions of TLR3, TLR4, TLR7, MyD88, and TRAF6 genes after IAV infection, and we preliminarily speculate that OMT may inhibit IAV proliferation and IAV viral pneumonia via inhibiting TLRs signaling pathways." (PMID 29570670, 2018).
vitamin D deficiency (5 papers, 2013 to 2023). A nutritional condition produced by a deficiency of VITAMIN D in the diet, insufficient production of vitamin D in the skin, inadequate absorption of vitamin D from the diet, or abnormal conversion of vitamin D to its bioactive metabolites. "Results showed that vitamin D deficiency increased pulmonary TLR2, TLR4 and dectin-1 expression at baseline both at mRNA and protein levels." (PMID 24926881, 2014). "Thus, vitamin D deficiency caused enhanced up-regulation of TLR2, TLR4 and dectin-1 in the lungs of mice both at baseline and post A. fumigatus challenge." (PMID 24926881, 2014). "We investigated whether vitamin D deficiency affects the expression of TLR2, TLR4, and dectin-1 on AMs at baseline by flow cytometry." (PMID 24926881, 2014). "Vitamin D deficiency increases the expression of hepatic mRNA levels of TLR-2, TLR-4, and TLR-9 in obese rats; however, calcitriol suppresses the expression of TLR-2 and TLR-4 protein and mRNA in human monocytes and triggers hyporesponsiveness to pathogen-associated molecular patterns." (PMID 23589715, 2013). "TLR4 and CD86 expression were not affected by vitamin D deficiency in our study." (PMID 23875738, 2013).
vulvovaginal candidiasis (5 papers, 2014 to 2026). Infection of the vulva and vagina with a fungus of the genus CANDIDA. "Genetic association of recurrent vulvovaginal candidiasis (RVVC) with polymorphisms in DECTIN-1, CARD9, TLR1, TLR2, and TLR4 genes." (PMID 25295030, 2014). "STRING analysis demonstrated that SYK, TLR4, CARD9, and TLR2 are involved in vulvovaginal candidiasis and infectious disease pathways." (PMID 37238269, 2023).
acute lymphoblastic leukemia (4 papers, 2014 to 2023). Leukemia with an acute onset, characterized by the presence of lymphoblasts in the bone marrow and the peripheral blood. "Sequence variants in genes coding for TLR4, MBL, and IL-1Ra were investigated in relation to clinical utility of identifying severe episodes of febrile neutropenia (FN) in a cohort of children undergoing treatment for acute lymphoblastic leukemia." (PMID 33339376, 2020). "In acute lymphoblastic leukemia (ALL) cell lines, TLR1, TLR2, TLR3, TLR4, TLR6 and TLR7 are expressed albeit at variable levels." (PMID 25112836, 2014). "In another study, the SNPs analysis on patients with newly diagnosed B-cell acute lymphoblastic leukemia (B-ALL) revealed the role of three specific TLR2 and TLR4 genotypes (TLR-2 Arg753Gln, TLR-4 Thr399Ile, and TLR-4 Asp299Gly) that could predict good B-ALL patients outcome." (PMID 37822929, 2023).
acute pyelonephritis (4 papers, 2010 to 2025). "TLR4 expression was significantly lower in chronic UTI patients than in acute pyelonephritis or healthy controls." (PMID 21151974, 2010). "The resulting infection triggers acute pyelonephritis, characterized by neutrophil infiltration and release of pro-inflammatory cytokines such as IL-1β, IL-6, and TNF-α via Toll-like receptor 4 (TLR4) activation on tubular epithelial cells." (PMID 40507440, 2025). "TLR4 expression in monocytes in patients with chronic UTI was significantly lower than in healthy controls and in patients with acute pyelonephritis (p = 0.03; 0.03)." (PMID 21151974, 2010). "The percentage of TLR4 expression in healthy controls, chronic UTI patients, and acute pyelonephritis patients was 8.57±2.88, 5.1±3.11 and 9.4±3.1%, respectively." (PMID 21151974, 2010). "The results of this study show that TLR4 expression in patients with chronic UTI is significantly lower than that in the control and acute pyelonephritis groups, suggesting that chronic UTI can be the result of reduced TLR4 expression, thereby effectively inducing innate immune response." (PMID 21151974, 2010).
acute sinusitis (4 papers, 2005 to 2023). "Compared with normal rats, the expression of TLR4-MyD88-NF-κB pathway-related genes in mRNA and protein levels of acute sinusitis rats were significantly increased." (PMID 34867331, 2021). "First, we verified that proteins related to the TLR4-MyD88-NF-κB signaling pathway were widely activated in rats with acute sinusitis." (PMID 34867331, 2021). "Based on this background, LMWH appears suitable for treating acute sinusitis by inhibiting the TLR4-MyD88-NF-κB pathway." (PMID 34867331, 2021). "Protein related to the TLR4-MyD88-NF-κB signaling pathway was activated in the acute sinusitis rat model, and LMWH can significantly inhibit its expression." (PMID 34867331, 2021).
age (4 papers, 2019 to 2026). A temporal measurement of the time period elapsed since an identifiable point in the life cycle of an organism. "In essence, our discoveries demonstrate that Hevin fosters age‐related cardiac dysfunction by activating cardiac macrophages via TLR4, prompting their polarization and CCL5 release." (PMID 41521391, 2026). "A previous study found that suppressing TLR4 expression is protective against age-related anxiety-like behavior in a sex-dependent manner." (PMID 32708167, 2020). "Future studies will fully explore the role of CS in accelerating senescence pathways and dissect the precise interactions amongst TLR4, HDAC2, and p16INK4a, which will offer additional molecular targets in treating a range of age‐related lung pathologies." (PMID 30790400, 2019).
anterior uveitis (4 papers, 2009 to 2016). Inflammation of the iris and anterior chamber of the eye. "In addition, the heightened ability to respond to LPS in inactive anterior uveitis patients may predispose these individuals to the development of ocular inflammation by LPS-mediated TLR4 activation." (PMID 19347047, 2009). "Recent studies using EIU models showed that the iris endothelium and ciliary body express TLR4, and TLRs play an important role in the pathogenesis of anterior uveitis." (PMID 25165412, 2014). "The blockage of this pathway by anti-TLR4 may signal a new direction in the treatment of acute anterior uveitis." (PMID 21264236, 2011). "Endotoxin-induced uveitis (EIU) in rodents is a model of acute Toll-like receptor 4 (TLR4)-mediated organ inflammation, and has been used to model human anterior uveitis, examine leukocyte trafficking and test novel anti-inflammatory therapeutics." (PMID 26794131, 2016).
aortic atherosclerosis (4 papers, 2014 to 2021). A atherosclerosis that involves the aorta. "As expected, down-regulated TLR4 expression by Ad-TLR4 siRNA caused remarkable decreases in aortic atherosclerosis lesions of CUMS mice." (PMID 25860573, 2015). "TLR4 is known as the receptor of LPS, and its deficiency significantly attenuated aortic atherosclerosis in ApoE-/- mice." (PMID 24502419, 2014). "Our previous study showed that elevated TLR4 expression and activated NF-κB activity were observed in aortic atherosclerosis lesions of CUMS apoE-/- mice." (PMID 25860573, 2015). "Interestingly, our previous study also showed that chronic unpredictable mild stress (CUMS) promoted the development of aortic atherosclerosis in apoE-/- mice, which may be related to activation of TLR4 and NF-κB in the aorta." (PMID 25860573, 2015). "To evaluate the effect of TLR4 siRNA and PDTC on the extent of aortic atherosclerosis, we measured the total lesion area by using en face preparation of the aorta and Soudan IV staining for lipids." (PMID 25860573, 2015).
bipolar disorder (4 papers, 2015 to 2024). A disorder of the brain that causes unusual shifts in mood, energy, activity levels and the ability to carry out day-to-day tasks. "Genotype frequencies of the studied TLR2 and TLR4 polymorphisms for the 531 bipolar disorder patients." (PMID 25790282, 2015). "The previous study reported the association of the TLR4 genotype with bipolar disorder." (PMID 38036661, 2024). "Finally, it is noteworthy that a genetic association has been found between bipolar disorder and polymorphism of Toll-like receptor 4 gene, which plays a major role in innate immunity." (PMID 26869176, 2016).
cervical tumor (4 papers, 2018 to 2022). "Few studies have shown an association between increased TLR4 expression in HPV-positive cervical tumor samples and resistance to apoptosis." (PMID 35468924, 2022). "Studies have indicated that inhibiting the TLR4/MyD88/NF-B and Wnt/β-catenin pathways inhibits the growth of cervical tumor.." (PMID 36185280, 2022). "In addition, activation of TLR4 by LPS in HPV positive cervical tumor derived cell lines resulted in higher TLR4 expression and resistance to apoptosis." (PMID 29472602, 2018).
channelopathy (4 papers, 2023 to 2025). Channelopathies are a group of diseases caused by the dysfunction of ion channel subunits or their interacting proteins. "Noteworthy is that Piezo2 channelopathy is also suggested to be linked to the TLR4/IL-6/TNF-α pathway." (PMID 37895134, 2023). "Accordingly, Piezo2 channelopathy, which has been suggested to be associated with IL-6 increases through the Hsp70/TLR4/Myd88/IL-6 pathway, as in DOMS, could lead to an imbalanced ratio of Th17/Treg in RA, therefore paving the way to the autoimmune response." (PMID 37108693, 2023). "It is noteworthy that the involvement of heat shock protein 70 (Hsp70) activation through the Hsp70/TLR4/Interleukin-6/TNF-α pathway is implicated in DOMS and theorized as the route to Piezo2 channelopathy." (PMID 40863771, 2025). "However, when Piezo2 channelopathy may become irreversible in ALS, the activated NF-κB pathway by TLR4/Myd88 signaling keeps on propelling the neuroinflammation in the CNS with non-resolving progressive impairment of the proprioceptive circuitry." (PMID 41155507, 2025).
chronic pancreatitis (4 papers, 2016 to 2024). A chronic inflammatory process causing damage and fibrosis of the pancreatic parenchyma. "TLR4 downregulation in spinal glial cells attenuates mechanical allodynia in a rat model of trinitrobenzene sulfonic acid induced chronic pancreatitis." (PMID 28545586, 2017). "However, further study is warranted in the area of TLR4 signaling and the polarization of macrophages as overproduction of M2 macrophages can result in chronic pancreatitis." (PMID 38585277, 2024). "Mice deficient in nucleotide-binding oligomerization domain 1 (NOD1) or Toll-like receptor 4 (TLR4), both of which are representative PRRs that recognize cell wall components derived from gram-negative gut bacteria, are resistant to experimental acute and chronic pancreatitis." (PMID 38440723, 2024). "Additionally, TLR2 and -4 gene expression was not significantly increased in tissue of chronic pancreatitis compared to normal tissue (TLR2 FD = 2.0 and TLR4 FD = 2.2, respectively)." (PMID 27941651, 2016).
clonorchiasis (4 papers, 2015 to 2024). Infection of the biliary passages with clonorchis sinensis, also called Opisthorchis sinensis. "TLR4 was involved in immune responses, including increased levels of tumor necrosis factor alpha and interferon gamma during clonorchiasis." (PMID 35127549, 2021). "Our data for the first time demonstrate that ESP of C. sinensis can potently induce secretion of pro-inflammatory cytokines via TLR4 in MIBECs, which suggests that TLR4 plays an important role in host defenses against C. sinensis and the pathogenesis of clonorchiasis." (PMID 26497121, 2015). "Thus, differentially expressed lncRNA Gm6135 may regulate the expression of TLR4 to induce inflammatory response in clonorchiasis." (PMID 35127549, 2021). "In our previous study, we showed dramatic changes of TLR2 and TLR4, and production of IFN-γ, IL-6, TNF-α, and IL-10 in the spleen were regulated by TLR4 as demonstrated in a murine model of clonorchiasis using TLR4 defective mice." (PMID 33489026, 2020).
colon adenocarcinoma (4 papers, 2018 to 2023). "The human colon adenocarcinoma cell line HT-29 used in our study possesses functional Toll-like receptor 4 signaling that is potentially important for zonulin secretion and has been used to study the effects of Lactobacillus strains on gliadin-induced zonulin secretion previously." (PMID 35495638, 2022). "MC111 was found able to increase TLR4 and P-gp expression in SW480 human colon adenocarcinoma cells; TLR4 involved pathway has been deeply studied considering also the effect on other targets such as the nuclear factor NF-κB." (PMID 35542423, 2018).
colon adenoma (4 papers, 2013 to 2020). An adenoma that arises from the colon. "We demonstrate that in humans, almost 40% of sporadic CRC and 20% of colon adenomas over-express TLR4." (PMID 23691015, 2013). "The differences were statistically significant (P<0.05), and the expression levels of IE1–72, TLR4 and TNF-α in the colon adenoma were evidently higher than those in normal tissue (P<0.05)." (PMID 25435993, 2015).
corneal ulcer (4 papers, 2009 to 2018). Area of epithelial tissue loss from corneal surface; associated with inflammatory cells in the cornea and anterior chamber. "Glucocorticoids, such as hydrocortisone, can inhibit the expression of TLR2 and TLR4 on HCFs, and thus may increase susceptibility to cornea infections." (PMID 19956406, 2009). "Another study demonstrated reduced inflammatory cell recruitment in Dectin-1 KO mice during a corneal infection model with Aspergillus, whereas cell recruitment was unimpaired in TLR2 KO or TLR4 KO mice; however, fungal killing was impaired in TLR4 KO mice." (PMID 29401615, 2018). "We found that neutrophils comprised >90% cells in corneal ulcers, and that there was elevated expression of TLR2, TLR4, TLR5 and TLR9, the NLRP3 and NLRC4 inflammasomes and the ASC adaptor molecule." (PMID 23750216, 2013).
coronary artery stenosis (4 papers, 2013 to 2019). "Moreover, the expression of inflammatory cytokines induced by TLR4 is significantly related to the degree of coronary stenosis within CAD patient groups." (PMID 28002812, 2017). "The present study demonstrated that the levels of TNF-α, TLR4, ACR, MDA, and hs-CRP as proinflammatory and prooxidant mediators were increased greatly in elderly patients with severe coronary stenosis and multiple coronary chronic total occlusions." (PMID 31780868, 2019). "Levels of TNF-α, TLR4, ACR, MDA, and hs-CRP were remarkably increased (P < 0.001), and levels of SDF-1α, SOD3, and eNOS were remarkably lowered (P < 0.001) in elderly patients with severe coronary stenosis and multiple coronary chronic total occlusions." (PMID 31780868, 2019).
diabetic foot ulcers (4 papers, 2013 to 2023). "In the case of TLR4 intronic SNP, rs1927911 has been reported to increase the risk of diabetic foot ulcers and atherosclerotic cerebral infarction." (PMID 31365550, 2019). "In contrast, clinical studies of diabetic foot ulcers in patients with Indian heritage found reduced levels of TLR‐4 signalling in diabetic foot ulcers with specific TLR‐4 SNP genotypes, displaying potential variation in how TLR‐4 is dysfunctional." (PMID 36564054, 2023).
diffuse large B-cell lymphoma (4 papers, 2008 to 2025). "Therefore, statistically significant, positive correlations with a signature found in TLR4, TLR9, and CD40 pathway activation were each associated with poor prognosis in diffuse large B cell lymphoma." (PMID 18937865, 2008). "A recent study found that A20 expression prevents diffuse large B-cell lymphoma (DLBCL) cell proliferation and migration by inducing TLR4/MyD88/NF-κB pathway-mediated autophagy in vitro." (PMID 40214497, 2025).
dry eye (4 papers, 2015 to 2024). "TLR4 activation by lipopolysaccharide (LPS) can induce dry eye development by increasing cytokine release in the cornea and conjunctiva." (PMID 38898418, 2024). "Therefore it is possible that altered tear quality in dry eye favors growth of TLR4-engaging bacteria at the ocular surface resulting in signals equivalent to high LPS concentration in our study thereby disrupting the immunomodulatory function of goblet cells and promoting inflammation." (PMID 25793763, 2015).
Duchenne muscular dystrophy (4 papers, 2022 to 2023). Duchenne muscular dystrophy (DMD) is a neuromuscular disease characterized by rapidly progressive muscle weakness and wasting due to degeneration of skeletal, smooth and cardiac muscle. "Another study involving TLR4 in Duchenne Muscular Dystrophy in a mouse model showed that TLR4 is a regulator of trained immunity." (PMID 36743677, 2022).
dyspepsia (4 papers, 2013 to 2025). An uncomfortable, often painful feeling in the stomach, resulting from impaired digestion. "In brief, CRP could attenuate dyspepsia by reducing the activation of inflammation-related TLR4/MyD88 and MAPK signaling pathways and by mediating gut microbial structure and composition." (PMID 40017602, 2025). "A case-control study comprising 284 ethnic Chinese individuals (70 non-cardia GC cases and 214 functional dyspepsia controls) was conducted for the genotyping of TLR2 -196 to -174del, CD14 -260 C/T and TLR4 rs11536889 using PCR, RT-PCR and mass spectrometry." (PMID 23565226, 2013).